PIK3CA (phosphatidylinositol-4,5-bisphosphate 3-kinase catalytic subunit alpha)
Diseases named in the same sentence as PIK3CA in open-access papers (continued):
Sharing a sentence is not in itself a finding about the gene and the disease.
breast cancer (continued). "Towards this goal, c-Myc amplification in a genetic model of PIK3CA-related breast cancer was discovered to circumvent PI3K-targeted treatment, in agreement with the observation that high MYC levels aligned with mutation of PIK3CA in patient samples." (PMID 28381598, 2017). "We molecularly profiled 861 patients’ primary breast cancers using an 800-gene expression panel, a 35-gene copy-number alteration (CNA) panel and a PIK3CA mutation assay." (PMID 28721382, 2016). "Of 18 response evaluable patients, 1 partial response was observed (ER+/HER2−/PIK3CA mutant breast cancer) and 4 patients had prolonged SD ≥ 24 weeks." (PMID 26686201, 2016). "Mutation of p110 alpha-catalytic subunit of phosphatidylinositol 3-kinase (PIK3CA) has high predictive and prognostic values for breast cancer." (PMID 27336598, 2016). "Collectively, these results reveal an essential role for mTOR in de novo lipogenic process particularly in HER2/PIK3CA-hyperactive breast cancer cells like MDA-MB-453." (PMID 27563814, 2016). "In summary, we have identified a novel and critical role of mTORC2 in oncogenic mechanism of HER2/PIK3CA-hyperactive breast cancer." (PMID 27015560, 2016). "Together, these results highlight an important mechanistic role for the rapamycin-resistant mTORC2 in survival of HER2/PIK3CA-hyperactive breast cancer cells via regulation of Bim and GSK3 activity." (PMID 27563814, 2016). "In this work, we show that inhibition of the constitutively active kinase PDK1 overcomes resistance to PI3Kα inhibitors in PIK3CA-mutant breast cancer cells insensitive to PI3Kα inhibition." (PMID 27451907, 2016). "Collectively, these results further support an important role for mTORC2-ACL axis in cell growth and therapeutic response in HER2/PIK3CA-hyperactive breast cancer." (PMID 27015560, 2016). "In breast cancer, a hyperactive AKT mediated by PTEN loss, PIK3CA, or AKT mutations resulted in resistance to anti-HER2 antibody, trastuzumab." (PMID 27826244, 2016). "Here we identify the novel lncRNA LINC00520 in breast cancer using two independent systems of cellular transformation driven by oncogenic v-Src and mutant PIK3CA, respectively." (PMID 27626181, 2016). "PIK3CA mutations were found in 7 (46.7%) luminal B, 4 (26.7%) luminal A, 3 (20.0%) basal-like and 1 (6.7%) HER2 subtypes (Breast cancer subtypes according to Perou and colleagues, 2000)." (PMID 26968814, 2016). "Breast cancer patient data were used to assess the clinical relevance of PIK3CA and PIK3CB in patients." (PMID 27792127, 2016). "Our study demonstrates that the IGF1R/p110β/AKT/mTOR axis confers resistance to BYL719 in PIK3CA mutant breast cancers." (PMID 27048245, 2016). "Recently, mTORC or CDK4/6 inhibition has been shown to sensitize PIK3CA mutant breast cancers to α-specific PI3K inhibitors." (PMID 27048245, 2016).
breast cancer (continued). "By contrast, LINC00520 is downregulated upon depletion of PIK3CA in SUM159-PT (mutant PIK3CA H1047L) breast cancer cells." (PMID 27626181, 2016). "We accomplished this by measuring cellular and molecular responses to lapatinib and the AKT inhibitors (AKTi) GSK690693 and GSK2141795 in a panel of 22 HER2+ breast cancer cell lines carrying wild type or mutant PIK3CA." (PMID 26181325, 2015). "More recent study revealed a synergistic effect existd between inhibitions of CDK 4/6 and PI3K in PIK3CA mutant breast cancer." (PMID 25990212, 2015). "PTEN loss (scores 0 and 1) occurred in 35.3% of sporadic breast cancer patients, including 4 who presented with both PTEN loss and PIK3CA mutation." (PMID 25816324, 2015). "Mutations in PIK3CA (the gene encoding the p110 catalytic subunit of PI3K) and PTEN loss of expression (LOE) have been detected in breast cancers." (PMID 26680641, 2015). "AKT1, KRAS and PIK3CA mutations and PTEN loss all exist in women with breast cancer in the mainland China." (PMID 25816324, 2015). "In fact, the combination of CDK 4/6 and PI3K inhibitors exhibited synergistic activity against PIK3CA mutant breast cancer cell lines." (PMID 26059247, 2015). "Preliminary reports about BYL719, a PI3K-α inhibitor, have shown promising activity in patients with heavily pretreated PIK3CA mutant breast cancer in a phase I study." (PMID 26059247, 2015). "Four of these PIK3CA mutant responders had breast cancer, indicating a potential molecularly selected tumour type for more focused clinical testing in the future." (PMID 26117819, 2015). "Based on this information, we tested the effect of PIK3CA mutations on cell and molecular responses to HER2 and AKT targeted inhibitors in 22 HER2+ human breast cancer cell lines." (PMID 26181325, 2015). "PIK3CA has also been suggested as a predictive marker for effective mTOR inhibition in breast cancer, unfortunately, a recent report on endometrial cancer did not support this." (PMID 25962426, 2015). "The breast cancer cell line MCF-7 and prostate cancer cell line LNCaP were also included since they display increased Akt phosphorylation due the presence of PIK3CA and PTEN mutations, respectively." (PMID 26402468, 2015). "Abnormal activation of PI3K/AKT/mTOR (PAM) pathway, caused by PIK3CA mutation, KRAS mutation, PTEN loss, or AKT1 mutation, is one of the most frequent signaling abnormalities in breast carcinoma." (PMID 25816324, 2015). "The fact that some cases without PIK3CA mutations had a moderate or high expression of PDK1 suggests that PDK1 can be independently activated in breast cancer and not only as part of the PIK3CA pathway." (PMID 24739482, 2014).
breast cancer (continued). "Genetic lesions in genes associated with this pathway, such as PIK3CA and PTEN, are among the most common such aberrations in breast cancer." (PMID 25153725, 2014). "These important result document interactions between HER2 and certain PIK3CA mutations and point to the possible co-targeting of HER2 and PI3K in certain breast cancers." (PMID 25051360, 2014). "Overall, the prevalence of PIK3CA mutations and PTEN low was 31% and 58%, respectively, which is within the range of reported frequencies in HER2-positive breast cancer." (PMID 25056500, 2014). "Our findings indicate that PDK1 is independently activated in breast cancer and not only as part of the PIK3CA pathway, suggesting that PDK1 plays a specific and distinct role from the canonical PIK3/Akt pathway and promotes oncogenesis independently of AKT." (PMID 24739482, 2014). "Phosphatidylinositol 3-kinase (PI3K) pathway deregulation (that is PIK3CA mutations and/or phosphatase and tensin homolog (PTEN) loss) has been shown to enhance breast cancer cell survival and confer resistance to chemotherapeutic agents." (PMID 25056500, 2014). "Mutations of PIK3CA and amplification of HER2 have been proposed to be useful biomarkers in breast cancer, whereas mutant Ras has been suggested to be a biomarker of resistance in several solid tumor cells." (PMID 24504419, 2014). "Additional studies by this group determined that co-inhibition of PI3K and EGFR suppressed growth and PI3K signaling in human breast cancer cells containing the mutant PIK3CA-H1047R gene." (PMID 25051360, 2014). "The effect of PIK3CA mutations and PTEN loss as prognostic factors has been evaluated extensively in breast cancer." (PMID 25056500, 2014). "PIK3CA mutations are common in ovarian CCC, endometrial and breast cancers and they are frequently co-mutated with ARID1A in ovarian CCC." (PMID 24559118, 2014). "PIK3CA mutations in ER+/HER2- luminal breast cancer actually result in low levels of mTORC1 expression and these breast cancers have some of the better treatment successes after 4HT therapy." (PMID 25051360, 2014). "Mutations at or deregulation of certain genes (BRCA1, BRCA2, HER2, PIK3CA) and others play important roles in breast cancer." (PMID 25051360, 2014).
breast cancer (continued). "All the Pik3ca-driven models have produced mammary tumors of varyinghistologies in contrast to single histology mouse models such as Neu, Myc and thepolyoma middle-T antigen." (PMID 25192370, 2014). "Further analysis revealed pathway-specific genetic driver mutations in breast cancer subtypes, such as BRCA1/2 alterations and PIK3CA alterations in basal-like and luminal breast cancers, respectively." (PMID 24874471, 2014). "Mutations of the PIK3CA gene, belonging to the third category,represent the most frequently reported molecular alterations of the PI3K signalingpathway in breast cancer." (PMID 25192370, 2014). "While PIK3CA displayed an overall correlation coefficient 0.4, it displayed high correlation in breast cancer (r = 0.9), head and neck squamous cancer (r = 0.8), and uterine/endometrial cancers (r = 0.7)." (PMID 24874471, 2014). "To verify the high frequency of PIK3CA mutations in TNBC tumors with elevated levels of AR protein, we analyzed the RNA-seq, DNA-seq and reverse-phase protein array (RPPA) data in TCGA breast cancer cohort." (PMID 25103565, 2014). "The mutational status of the PIK3CA gene and expression of PTEN was examined in breast cancer specimens that differed in the state of malignancy (e.g., primary vs. metastatic breast cancer from the same cancer patient)." (PMID 25051360, 2014). "Although a number of studies regarding the PIK3CA gene or PI3K pathway in HER2-positive breast cancer have been reported, they mainly focused on the impact on prognosis or response to anti-HER2 therapy in a metastastic disease." (PMID 25542038, 2014). "Genetic and genomic alterations in the PI3K pathway were previously found in all breast cancer subtypes, with basal-like cancers having more loss of pathway inhibitors PTEN and INPP4B, and with luminal A cancers having more mutations in PIK3CA." (PMID 24386073, 2013). "These new results suggest that PIK3CA mutations and PIK3R1 underexpression are associated with opposite prognostic impacts on breast cancer patient survival." (PMID 24229379, 2013). "Altogether, we observed PIK3CA and/or PIK3R1 and/or AKT1 mutations in 174/454 (38.3%) breast cancer tumors." (PMID 24229379, 2013). "Dr Jose Baselga from New York, USA, opened the scientific session with an outstanding and comprehensive talk on the role of PIK3CA inhibitors in subtypes of breast cancer." (PMID 23589728, 2013). "To model the oncogenic PIK3CA-driven early stages of human cancer, we employed the clonal breast cancer cell line MCF10DCIS.com, which was derived from a xenograft originating from premalignant MCF10AT cells that were injected into SCID mice." (PMID 23986086, 2013). "The present study focused on the prognostic roles of PIK3CA and PIK3R1 genes and additional PI3K pathway-associated genes in breast cancer." (PMID 24229379, 2013). "PIK3CA, PIK3R1 and AKT1 mutations were mutually exclusive and were observed in a total of 175 breast cancer tumors." (PMID 24229379, 2013).
breast cancer (continued). "The highest mutational frequency for all of the genes assessed in this study (PIK3CA and/or PIK3R1 and/or AKT1) was observed in HR+/ERBB2- tumors (133/289; 46.0%), while mutations were observed in up to 28% of cases in other breast cancer subtypes." (PMID 24229379, 2013). "Interestingly, the sensitivity to SREBP depletion was not restricted to RPE cells but could also be demonstrated in a panel of breast cancer cell lines in which the PI3-kinase pathway is activated by loss of function of PTEN or activating mutations in PIK3CA or KRAS." (PMID 24280005, 2013). "In conclusion, we found significantly increased PIK3CA expression in breast carcinoma tissue compared to normal breast tissue." (PMID 24083111, 2013). "Our data showed significantly higher PIK3CA expression in breast carcinoma tissue than in normal breast tissue, a consistent finding even after stratifying for oestrogen receptor and HER2 receptor status as well as for tumour histology." (PMID 24083111, 2013). "Breast cancers with simultaneous human epidermal growth factor receptor 2 (HER2) amplification and PIK3CA mutation represent good examples of simultaneous RTK hyperactivity and activation of the PI3K pathway at several levels." (PMID 23232172, 2012). "The agreement between our data and previously published data on the effects of PIK3CA on breast cancer cell lines helps to validate the efficacy of the CBC-1 for screening of targeted therapies for breast cancer." (PMID 23049944, 2012). "The tumor types of these responders were estrogen receptor positive breast cancer, cervical cancer and KRAS-mutant colon cancer, and PIK3CA mutations were detected in all three cases (E542K/V, E545K and R88Q respectively)." (PMID 23232172, 2012). "According to previous studies, specific genetic alterations, such as HER2 amplification and PIK3CA mutation, were revealed as biomarkers for sensitivity to the PI3K inhibitor in breast cancer." (PMID 22159814, 2012). "For example, a recent study by Brough and coworkers, which screened the effects of various siRNAs on a number of breast cancer cell lines, also found PIK3CA siRNA to significantly decrease the viability of SK-BR-3 and MCF7 cells." (PMID 23049944, 2012). "ERBB2 amplification and PIK3CA mutation were validated as biomarkers for sensitivity to the single-agent phosphoinositide 3-kinase (PIK3) inhibitor, GDC-0941, in breast cancer models." (PMID 23056620, 2012). "In mice bearing ER+, HER2-negative, PIK3CA-mutant MCF-7 breast cancer xenografts, treatment with the combination of fulvestrant and BKM120 induced tumor regression." (PMID 23087906, 2012). "Mutation of the PIK3CA gene, which encodes the p110α catalytic subunit of PI3K, leads to activation of Akt and is found in 18% to 40% of human breast cancers." (PMID 21492444, 2011). "To model PIK3CA-mutant breast cancer we generated mice with an H1047R mutant Pik3ca cDNA targeted to the ubiquitously expressed ROSA26 locus (R26)." (PMID 21646685, 2011). "Since PIK3CA mutation has been reported to be associated with a more favorable prognosis, however, it was unclear how many patients with ER-positive PIK3CA mutant breast cancer would present with advanced disease." (PMID 21362200, 2011). "BEZ235 has been reported to inhibit growth and proliferation and induce apoptosis in a variety of tumor cell lines, including breast cancer cells with mutant or amplified PIK3CA." (PMID 22039466, 2011).